INS (insulin)
Diseases named in the same sentence as INS in open-access papers (continued):
Sharing a sentence is not in itself a finding about the gene and the disease.
Insulin resistance (continued). "Hyperinsulinemia, taken as fasting insulin ≥12.2 μUI/ml (84.73 pmol/L), was also more frequent in PCOS (41.8%), and PCOS-with-SCH patients (32.2%) than in controls (10.4%) (p<0.001); PCOS and PCOS-with-SCH had similar prevalences of imputed insulin resistance (p=0.293)." (PMID 28868249, 2017). "Insulin resistance was demonstrated not only by the increased HOMA-IR index but also by augmented TG/HDL-c ratio and the TyG index, which have previously been used as surrogate measures of impaired insulin sensitivity in obese adolescents with normoglycemia, in prediabetes, as well as in T2DM." (PMID 28635632, 2017). "Hyperglycemia developed when enhanced insulin secretion could no longer compensate for insulin resistance." (PMID 29152121, 2017). "Studies focusing on the insulin resistance and dysglycemia suggested that, compared to participants with NGT, patients with IGT or impaired fasting glycemia (IFG) had higher levels of HOMA-IR, which indicated that patients with postchallenge hyperglycemia tended to be more insulin resistant." (PMID 28913363, 2017). "Hyperleucinamia in a T2DM mouse model showed that retromer trafficking was impaired, with decreased levels of hVps34 reported, whereby hyperleucinemia may account in part for insulin resistance and driving mTORC1 activation independent of insulin." (PMID 28626421, 2017). "This means that insulin might not stimulate ENaC-mediated renal Na+ reabsorption due to insulin resistance, even under hyper-insulinemia conditions in DM." (PMID 28805732, 2017). "Experimental studies have shown that: (i) inhibition of JNK in the liver leads to a beneficial effect on insulin resistance and glucose tolerance 49; (ii) JNK is abnormally activated in obesity 28 and (iii) its absence leads to a decrease in adiposity and to an improvement in insulin sensitivity." (PMID 27106634, 2017). "Although we did not measure beta cell function and insulin sensitivity in the current study, hyperinsulinemia/insulin resistance and/or leptin resistance may be related to glucose fluctuation and/or incidence of hypoglycemia." (PMID 28683829, 2017). "To further test whether PTPR-γ is required for inflammation-induced insulin resistance we compared the effect of LPS treatment on insulin sensitivity in mice lacking PTPR-γ and their intact controls." (PMID 29180649, 2017). "A significant correlation between ghrelin levels and insulin resistance was found in PCOS women; treatment with metformin improved insulin sensitivity and enhanced serum ghrelin levels, suggesting that its reduction in PCOS may be a cause or a consequence of insulin resistance." (PMID 27473078, 2017). "Gestational diabetes mellitus may appear in healthy non-diabetic females, due to gestational insulin resistance that leads to increased blood sugar levels and hyperinsulinemia (increased insulin production from the pancreatic beta cells)." (PMID 28929027, 2017). "If the insulin released from pancreatic β-cell failed to adequately bind or trigger the signal transduction pathway that leads to its expected physiological response, a condition known as insulin resistance is developed." (PMID 29023424, 2017). "However, in our cohort of patients with acute-on-chronic insulin resistance, we observed a greater percentage increase in c-peptide levels in insulin-treated patients than in patients not receiving insulin during hyperglycemia." (PMID 28497374, 2017). "However, neither group experienced changes in insulin resistance assessed using an insulin-augmented frequently sampled intravenous glucose tolerance test measured after a non-restricted day." (PMID 28106818, 2017). "On the other hand, studies among sub-Saharan Africans with type 2 diabetes have found variable insulin resistance in these individuals compared with individuals without type 2 diabetes, but fast declines in insulin secretion after diagnosis with type 2 diabetes." (PMID 28144712, 2017).
Insulin resistance (continued). "We hypothesized that leptin and osteocalcin would be negatively related to one another, and that leptin would be a negative predictor of serum glucose, insulin and insulin resistance." (PMID 28286536, 2017). "DM is a metabolic disorder categorized into two main groups: Type I (Insulin dependent) that is due to immune-mediated beta-cells destruction and lead to insulin deficiency, and Type 2 (Non-Insulin dependent) that is due to insulin secretion defects and resulted in insulin resistance." (PMID 28927401, 2017). "Specifically, statistically significant positive effects were identified for systolic blood pressure, hemoglobin A1c, and creatinine, but not for fasting glucose, homeostatic model assessment of insulin resistance, diastolic blood pressure, insulin, triglycerides, LDL, or HDL cholesterol." (PMID 28989978, 2017). "Because GLP-1 improves insulin resistance without causing hypoglycemia, GLP-1, unlike insulin, might exert neuroprotective effects while safely being administered by many routes." (PMID 28649604, 2017). "However, there was no significant negative correlation of 18F-FDG uptake with plasma insulin levels or insulin resistance." (PMID 28715453, 2017). "None had a significant relationship (p = 0.001 or better) with log homeostasis model assessment-estimated insulin resistance (HOMA-IR), although LPC14:0 had the strongest relationship (p = 0.004) and may be the main mediator of the effect of dairy on insulin sensitivity." (PMID 28817063, 2017). "In this respect, it should be important to mention that impairment of insulin functions or insulin resistance may lead to hypertension, but no mechanistic information is yet available on the development of this disease." (PMID 28811499, 2017). "This suggests that factors other than adiposity may contribute to insulin resistance in NAFLD, which is compatible with our present finding that the severity of histological findings affects insulin sensitivity in NAFLD independently of BMI in multiple regression analysis." (PMID 28878826, 2017). "However, inflammation is not the only mechanism of insulin resistance and fatty liver in obesity, various abnormalities of lipid metabolism can also impair insulin signaling." (PMID 28736524, 2017). "Therefore, several other indirect methods are suggested for detection of IR, including fasting insulin (FI), fasting blood sugar (FBS)/FI, Homeostatic Model Assessment of Insulin Resistance (HOMA-IR), Quantitative Insulin Sensitivity Check Index (QUICKI), and MacAuley index (MCA)." (PMID 29177243, 2017). "However, the tissue triglyceride content was not absolutely related to the development of insulin resistance, because only the skeletal muscle had progressed to decreasing insulin sensitivity." (PMID 29046729, 2017). "For example, dysregulation of insulin-IGF-1 axis, sex hormones, or adipokines in obese individuals might result in multiple systemic metabolic alterations, such as insulin resistance, hyperglycemia, and chronic inflammation that can contribute to increased cancer risk in such patients." (PMID 28678173, 2017). "Thus, CLW improved the diabetic symptoms by suppressing hepatic insulin resistance by potentiating hepatic insulin signaling as much as rosiglitazone in non-obese type 2 diabetic rats with impaired insulin secretion." (PMID 29104217, 2017). "What our data highlights is that beyond the effects that are known to be driven by insulin mediated pathways, there could be additional routes leading to the observed metabolic shifts, independent of hyperinsulinemia or insulin resistance." (PMID 28567337, 2017). "In sub-Saharan Africans, the prediabetes phase (defined as IFBG in this study) was suggested to be characterised by insulin resistance rather than failure of insulin secretion; per SD increase of HOMA-IR the odds for IFBG were 3.26 compared with 1.13 for 1 SD increase in HOMA-B." (PMID 28144712, 2017).
Insulin resistance (continued). "Impaired glucose tolerance was markedly improved by CE treatment, and insulin sensitivity was restored to normal levels, as assessed by the IPGTT and ITT, indicating that CE exerted a long-term effect on blood glucose regulation via improvement of insulin resistance." (PMID 28091547, 2017). "The apparent greater reductions in HOMA insulin resistance with a two day IER compared with CER in premenopausal women who are overweight or obese, and in some relevant animal models raises the possibility that IER may improve hepatic insulin sensitivity." (PMID 28106818, 2017). "MiR-16 has been reported to play a key role in regulation of insulin signaling through a reduction in TNFα and suppressor of cytokine signaling 3 (SOCS3) signaling and increase in insulin-like growth factor binding protein-3 (IGFBP-3) levels to inhibit insulin resistance." (PMID 29214180, 2017). "The ability of liver to store glycogen is impaired due to lack of insulin or insulin resistance." (PMID 28166749, 2017). "Previously, using 31P phosphorus magnetic resonance spectroscopy (MRS) in nondiabetic Asian Indians with NAFLD, we reported increased insulin resistance and deranged gluconeogenesis pathway correlating with body mass index, body fat percentage, waist circumference, and fasting serum insulin levels." (PMID 28634585, 2017). "Further studies are therefore warranted in animals treated with lipid to induce acute insulin resistance without weight gain to determine whether weight loss is involved in the effect of PDX on both glucose and insulin tolerance." (PMID 28469249, 2017). "Researchers have found that the A3243G form of mitochondrial diabetes is related to decreased glucose-induced insulin release, but is not characterized by insulin resistance, indicating that the major pathology occurs within mitochondria of pancreatic beta cells." (PMID 28930273, 2017). "In terms of insulin resistance, plasma insulin levels in 8-month-old Cox7rpKO mice were not elevated in OGTT, suggesting that the fasting-induced hypoglycemia in Cox7rpKO may not be solely explained by the increase in insulin resistance." (PMID 28790391, 2017). "Alternative M2 macrophages sustain insulin sensitivity via the secretion of anti-inflammatory cytokines such as IL-4 and IL-13, while classical M1 macrophages secrete pro-inflammatory cytokines such as TNF-α, IL-6, and IL-1β, which, in turn, leads to insulin resistance and NASH." (PMID 28420094, 2017). "Therefore, increased insulin clearance and IDE expression could be another beneficial effect of exercise on the treatment and/or prevention of diseases related to insulin resistance." (PMID 27467214, 2016). "However, impaired insulin secretion rather than insulin resistance was suggested to represent the predominant mechanism underlying PTDM." (PMID 26735686, 2016). "In insulin resistance and endothelial dysfunction, a hyperactivity of the renin-angiotensin-aldosterone system (RAAS) plays a crucial role, and therefore targeting it on a different molecular level benefits in improvement in insulin sensitivity and vascular function." (PMID 27413253, 2016). "Third, we could not evaluate the direct effects of insulin resistance because we did not obtain data regarding insulin levels." (PMID 28070183, 2016). "Elevated insulin signalling in the hepatic PV zone in the fasting state, and not that in the fed state (that is, absence of reduction of insulin signalling even in the fasting state) seems to be responsible for the enhanced lipogenesis under the condition of ‘selective insulin resistance'." (PMID 27708333, 2016). "Randomised trials of the effects of high-egg diets (2–3 eggs/day for 6–12 weeks) on markers of glycaemic control and insulin resistance have generally found no change in fasting plasma glucose levels, the postprandial response to glucose, HbA1c or fasting insulin levels." (PMID 26993632, 2016).
Insulin resistance (continued). "However, patients eventually fail to compensate for insulin resistance because increased insulin secretion does not normalize serum glucose levels by reducing insulin resistance." (PMID 26978400, 2016). "Consistently, APN treatment in SH-SY5Y cells with insulin resistance and overexpressing Aβ induce higher pAkt levels through AdipoR1 upon insulin treatment whereas the induction was blocked by compound C, indicating APN can enhance neuronal insulin sensitivity through AMPK activation." (PMID 27884163, 2016). "Moreover, constitutive deletion of IR in the liver has been reported to impair insulin signalling but does not induce chronic insulin resistance or hyperinsulinemia, probably owing to the hepatic dysfunction developed in these mice." (PMID 27562101, 2016). "The classic indexes (HOMA, QUICKI, FIRI) used to evaluate insulin sensitivity were calculated using the fasting blood glucose concentration and the fasting serum insulin concentration, and only the HFA group showed marked insulin resistance compared with the control group (P<0.05)." (PMID 26745179, 2016). "To examine whether these phenomena were caused by decreased insulin production or insulin resistance, we calculated the HOMA-IR values, which confirmed that glucose regulation was derived from insulin production rather than insulin resistance." (PMID 27736926, 2016). "However, the degree of insulin resistance was identical in NHA2 KO mice, indicating that also in the setting of diet-induced obesity, loss of NHA2 per se does not alter insulin sensitivity." (PMID 27685945, 2016). "Insulin resistance, a known side effect of GC therapy, contributes to muscle atrophy via reduced protein synthesis and increased protein degradation by genomic and non-genomic interference with several kinases in the insulin-signaling pathway." (PMID 26875982, 2016). "Furthermore, it has been proposed that increased adipose ChREBPβ expression, but not ChREBPα, correlates with insulin sensitivity in humans and conversely, a decreased expression in adipose tissue and increased expression in liver predicts insulin resistance." (PMID 27992582, 2016). "In fact, it has been shown that obestatin potentiated glucose-induced insulin secretion at normal glucose levels, but not at high glucose levels, further confirming the observed relationship and the contribution of obestatin with insulin resistance." (PMID 27348010, 2016). "However, the selective insulin resistance we observed in PHHs is more akin to a T2DM state in humans in which insulin fails to suppress gluconeogenesis but continues to activate lipogenesis, thereby leading to hyperglycemia, hypertriglyceridemia and steatosis." (PMID 27312339, 2016). "The insulin resistance index calculated by the HOMA model (HOMA-IR) using fasting serum levels of insulin (μIU/mL) and glucose levels (mmol/L) indicated that males and females of OF1-HCD group as well as females of MF1-HCD were insulin resistant compared to CF1-CD and CF1-HCD groups at the 5th week." (PMID 27200209, 2016). "For example, normotensive, first-degree relatives of patients with high blood pressure are insulin resistant when compared to normotensive individuals without a family history of hypertension, and surrogate markers of insulin resistance predict incident hypertension." (PMID 27001495, 2016). "However, in our study because of insulin resistance and hyperinsulinemia, cells are not able to consume glucose under the effect of insulin but cells increased its internal gluconeogenesis under effect of Origanum." (PMID 28228803, 2016). "Consequently, the lack of ARNT in the skeletal muscle did not affect weight gain, lean/fat mass, insulin sensitivity and glucose tolerance in lean mice, nor did it impact insulin resistance and glucose intolerance in high fat diet-induced obesity." (PMID 28005939, 2016).
Insulin resistance (continued). "The current results show that performing a low dose of moderate or high intensity exercise may induce benefit for insulin secretion when adjusted to skeletal muscle, but not liver or adipose, insulin resistance in people with reduced β-cell function." (PMID 27111219, 2016). "Additionally, regardless of macronutrient type, acute elevations in insulin and insulin resistance have been observed the morning after pre-sleep caloric intake in obese women." (PMID 27472361, 2016). "However, under conditions of insulin resistance, where passive uptake dominates rather than insulin-stimulated scavenging, the simulated gradient in the rate of FFA uptake across the sinusoid was less steep." (PMID 27632189, 2016). "In this study, rats were treated with a HFD for 8 weeks to establish an animal model of hepatic insulin resistance, and high glucose-induced HepG2 cells were used to establish a cell model, which were used to investigate the effect of DMY on glucose metabolism and insulin signaling." (PMID 27796348, 2016). "IL-6 is one of the most studied inflammatory cytokine, which modulates insulin resistance via numerous mechanisms such as the c-Jun N-terminal kinase 1 (JNK1)-mediated serine phosphorylation of IRS1, with elevated circulating IL-6 levels observed in insulin-resistant subjects." (PMID 26842399, 2016). "Furthermore, insulin tolerance test (ITT) showed that the slope of glucose reduction in BCH-treated mice at 0.5 h was steeper than that of BCH-untreated HF/HFr-fed mice, supporting that the BCH treatment improved insulin resistance." (PMID 27874078, 2016). "However, because FOXO1 dysregulation must precede dysregulation of insulin control of MARCH1, this phenomenon is likely to be consequence rather than cause of insulin resistance." (PMID 27577745, 2016). "Serum cortisol levels were correlated with insulin secretion, but not with insulin resistance." (PMID 27861636, 2016). "In addition, GEB potentiated glucose-stimulated insulin secretion by increasing β-cell mass and enhanced peripheral insulin resistance in a non-obese and insulin-insufficient type 2 diabetic animal model." (PMID 26978400, 2016). "Several studies support the BPA detrimental effect on pancreatic β cells, with the consequent impairment of insulin secretion and glucose metabolism, but also suggest an “obesogen” action of BPA by affecting adipocyte metabolic functions, with the consequent development of insulin resistance." (PMID 27782064, 2016). "However, the flexibility of IMCL is not related to insulin resistance alone, but is regulated by a complex interplay including diet, fat availability, physical exercise, and insulin action." (PMID 27649157, 2016). "Since skeletal muscle glucose uptake is the central factor in maintenance of insulin sensitivity and development of T2DM, it will be important to elucidate the role of genistein in skeletal muscle mitochondrial capacity in a model of progressive insulin resistance." (PMID 26973284, 2016). "The level of serum insulin may be increased due to increased insulin resistance, an indication that the cells are non-responsive to insulin." (PMID 27827939, 2016). "It did not seem that insulin resistance or insulin secretion influenced our observations, but other factors such as specific pregnancy hormones may be implicated and merit future investigations." (PMID 27004421, 2016). "APN deficiency is associated with peripheral insulin resistance in mice and human, causing T2DM and DM-related syndromes, whereas whether adiponectin is associated with cerebral insulin sensitivity has not been documented." (PMID 27884163, 2016). "However, daily insulin dose did not correlate with arterial 18F-FDG uptake, whereas plasma insulin concentrations and indices of insulin resistance were highly correlated with 18F-FDG-uptake." (PMID 27887576, 2016).